MIB1 (MIB E3 ubiquitin protein ligase 1)
Diseases named in the same sentence as MIB1 in open-access papers (continued):
Sharing a sentence is not in itself a finding about the gene and the disease.
tumor (continued). "Immunostaining also showed a low score for MIB-1, which is a monoclonalantibody recognizing Ki-67, a marker of proliferating cells in tumor tissue." (PMID 35111517, 2020). "The biphasic tumor presented with Rosenthal fibers, eosinophilic granular bodies, and few mitoses (7/10HPF), and MIB1 labeling index was estimated at 10%." (PMID 31677015, 2020). "We obtained a significant result by decoloring H&E-stained tumor sections and then immunostaining them with an anti-Ki67/MIB1 antibody." (PMID 32466184, 2020). "This biphasic tumor presented with a very elevated mitotic count (17 mitoses for 2.3 mm2), necrosis, and microvascular proliferation The MIB1 labeling index was estimated at 30%." (PMID 31677015, 2020). "Co-immunofluorescene staining demonstrates on a cellular level, that Mib1-positive tumor cells express glial fibrillary acidic protein only very sporadically." (PMID 32391260, 2020). "Since elevated MIB-1 is predictive of the regrowth potential of a tumor after initial surgery, additional referral to oncology with subsequent intervention was performed." (PMID 32983369, 2020). "As a marker for tumor proliferation, MIB1 expression was quantified for all evaluated tumor samples." (PMID 31291992, 2019). "Overall, the MIB1 index is usually quite low within this slow growing tumor entity, with only 4 cases with indices over 4% in this study cohort of 1048 cases." (PMID 31291992, 2019). "We performed a multivariate analysis, including gender, ASA-intake, prior RT and presence of NF2, tumor extension together with patient age and MIB1 expression." (PMID 31291992, 2019). "Staining with Ki-67/MIB1 was positive in approximately 30% of the tumour cells, indicating a rather high mitotic index." (PMID 30522494, 2018). "High cVEGF expression was present in 61.7% of younger patients (p = 0.006), and it showed a significant association with positive lymph node status (p = 0.010), higher tumor histological grade (p = 0.020), MIB1 positive expression (p < 0.001)." (PMID 29716631, 2018). "For Ki-67, MIB-1 index of primary tumor was 30–50%, whereas that of the present tumor was less than 80%." (PMID 29299698, 2018). "Ki-67 (MIB-1) showed a < 10% proliferative index for all cases (1000 tumor nuclei counted) (median: 1.1, mean: 1.97, range: 0–9.4)." (PMID 30340515, 2018). "Tumor mitotic activity results were reported in only 41 patients (Ki-67 in 5 patients (5.3%) the highest below 5%, MIB-1 in 6 patients (6.3%) the highest < 5%, and low mitotic count in 30 (31.6%) with a mean of 2.1/50 and a median of 1/50 high-power fields)." (PMID 29970075, 2018). "Immunohistochemical staining performed on MIB1+ (i.e., proliferating) areas of the tumor confirmed high intracellular levels of NAMPT in live human xenografts in both BiR cell lines." (PMID 29721178, 2018). "The grade of the neoplasms is determined by tumour morphology along with the proliferation (Ki-67) index (assessed with the MIB1 antibody) and the mitotic index according to World Health Organisation (WHO) classification." (PMID 29599916, 2018). "Whereas, miR-9-3p expression positively correlated with ki67/miB1 stained cells (r = 0.20, p = 0.042) and negatively correlated with age (r = −0.21 p = 0.022), tumour dimension (r = −0.21 p = 0.019) and ER expression (r = −0.25; p = 0.005)." (PMID 28345661, 2017). "MIB-1 labeling index (LI) has shown to correlate with tumor growth and has been suggested as a supplement for the histopathological grading for estimation of recurrence risk in several studies." (PMID 28953948, 2017). "In the log-rank test, deep tumor location, MIB-1 positivity, large tumor size (≥5 cm), and HIF-1α positivity were significant poor prognostic factors." (PMID 28558056, 2017). "Immunoreactivity was confined to the tumor cell nuclei for MIB-1 whereas survivin revealed both nuclear and cytoplasmic reaction." (PMID 28953948, 2017).
tumor (continued). "Immunoreactivity was confined to the tumor cell nuclei for MIB-1 and topoisomerase IIα, but some cytoplasmic reaction was observed for mitosin." (PMID 28301542, 2017). "By contrast, miR-9-3p expression negatively correlated only with ER expression, patient’s age and tumour dimension, and positively correlated with ki67/miB1 expression." (PMID 28345661, 2017). "Consistent MIB-1 detection in tumor tissues makes it a better proliferation marker than proliferating cell nuclear antigen (PCNA)." (PMID 29312841, 2017). "Significant associations emerged between EGFR amplification and large tumor size (T4), ER-negative and HER2-positive status, between CCND1 amplification and HER2-positive and MIB1-positive status, and between ESR1 deletion and ER-negative status." (PMID 27765917, 2016). "Statistically significant differences emerged in the distribution of EGFR, CCND1 and ESR1 CNVs according to ER, HER2, MIB1 and tumor size (T) status." (PMID 27765917, 2016). "Numerous biomarkers have been proposed as prognostic markers in invasive BC; however, stratification of tumors into prognostic groups to guide therapeutic decision is based mainly on tumor stage and grade and on assessment of ER, PR, MIB1 and HER2 status." (PMID 26312763, 2015). "p-4EBP was correlated with large tumor size (p = 0.0316), the existence of metastasis (p = 0.0014), >10 % MIB-1 LI (p = 0.0095), and higher AJCC stage (p = 0.0173)." (PMID 26502919, 2015). "High stromal CTGF expression was positively correlated with high MIB1 proliferation index in tumor epithelial cells (= />15%) (p = 0.034)." (PMID 25738829, 2015). "Immunohistochemical staining shows that most tumour cells are positive for MIB-1, vimentin, EMA, WT-1, and CD57; in contrast, CK7 staining exhibits weak focal positivity." (PMID 25907695, 2015). "MIB-1 LI correlated with tumour size (p = 0.012) and was positively related with male gender (p = 0.23) and partial surgical resection (p = 0.036)." (PMID 26019536, 2014). "In contrast, the melanocytosis samples after MEK162 treatment all showed lower MIB-1 expression with a MIB-1 LI of <1%, suggesting little tumor heterogeneity throughout the tumor as far as proliferative activity is concerned." (PMID 24713450, 2014). "Immunohistochemistry has shown the tumor cells to be positive for GFAP, EMA, monoclonal antibody of cell proliferation-associated nuclear antigen (MIB-1) and cell cycle-associated nuclear antigen Ki-67." (PMID 24348765, 2014). "All of the lesions in our RIM case had high MIB-1 labeling indices, and the tumor recurred postoperatively within 1 year." (PMID 24767145, 2014). "Morphologically, MIB-1 immunoreactive triple negative breast tumors display comedo-type necrosis and infiltrative tumor margin each in 64% (23/36 cases), tumor giant cells in 83% (30/36 cases) and lack of stromal inflammation in 78% (28/36 cases)." (PMID 24586570, 2014). "For the classifiers of the intermediate-risk group, three risk factors were designated based on univariate analyses: patients' poor preoperative KPS, incomplete tumor resection, and tumors with high MIB-1 labeling indices." (PMID 24820480, 2014). "The Ki67/MIB-1 and Mcm2 immunostaining revealed distinct positive tumour cell nuclei heterogeneously distributed within the tumour tissue." (PMID 23618321, 2013).
tumor (continued). "The proliferative activity can be assessed by counting mitoses per unit area of the tumour usually expressed as mitoses per 10 high power field or as the percentage of immunostaining for the cell cycle-dependent proliferation marker Ki67 (MIB1) antigen." (PMID 23997766, 2013). "Factors significantly related to shorter DFS, shorter OS, tumour-related death and higher risk of recurrences/distant metastases included high MIB-1 LI and high uPA and MMP-9 expressions by tumour-adjacent fibroblasts." (PMID 23289974, 2013). "The fraction of MIB-1-positive tumor cells (the MIB-1/Ki-67 labeling index) is often correlated with the clinical course of cancer; Ki-67is of prognostic value for many types of malignant tumors." (PMID 23229269, 2013). "The positive correlations between mitotic counts, Mcm2 PIs, and Ki67/MIB-1 PIs found in this study are in accordance with studies on other human tumours." (PMID 23618321, 2013). "The tumor size, PVI, ER status, expression of MIB1 and HIF-1α were all significant factors strongly associated with worse prognosis (p = 0.031, p = 0.000, p = 0.000, p = 0.001 and p = 0.011, respectively)." (PMID 22439624, 2012). "Poor prognosis is also related to an older patient age, retroperitoneal location, and high MIB-1 labeling index ≥10% of tumor cell population." (PMID 22953099, 2012). "Proliferation markers as MIB-1 (directed against the Ki-67 antigen), were expressed in less than 2% of the tumor cells nuclei." (PMID 23021468, 2012). "On the contrary, increased cell cycling and MIB-1 LI suggest more aggressivebehavior of promote tumor progression and metastasis in variety of cancers." (PMID 22734595, 2012). "Out of 187 cancers, 87 (46%) were grade 2 and these statistically inversely correlated with the PVI (p = 0.000), tumor size (p = 0.036), nodal status (p = 0.012) and MIB1 (p = 0.000), and directly correlated with ER (p = 0.000) and PR (p = 0.025) status." (PMID 22439624, 2012). "The proliferation marker MIB-1 (directed against the Ki-67 antigen) helps to determine tumor grade and prognosis." (PMID 23021468, 2012). "It is clear that in paediatric HGG in this study, expression of MiB-1 is highly variable across individual tumours." (PMID 22311740, 2012). "When we correlated SLC22A1 expression with clinicopathological characteristics, the most striking result was a significant inverse correlation between expression of SLC22A1 protein and the tumor proliferation rate MIB1/Ki-67." (PMID 22196450, 2011). "New antibodies reactive against proliferation-associated antigens have been launched and shown to correlate with tumour grade, mitoses, and Ki-67/MIB-1." (PMID 21609421, 2011). "Univariate COX analyses with overall survival as the dependent variable, demonstrated significant correlation to KPS (p < 0.001), tumour surgery (p < 0.001), age (p = 0.016), pHH3 index (p = 0.018), and Ki-67/MIB-1 (p = 0.031)." (PMID 21609421, 2011). "Proliferation is a key feature of tumor progression and it is widely estimated immunohistochemically using the Ki67 antibody MIB-1." (PMID 21819622, 2011). "Mib-1 immunoreactivity was confined to the nucleus with varying intensity of reactivity and high expression at the invasive tumour periphery." (PMID 20716163, 2010). "Approximately 5%-10% of T cells within the DC T cell clusters at the tumour border showed signs of proliferation, as shown by nuclear expression of the proliferation marker Ki67 (Mib-1)." (PMID 20969772, 2010). "Immunohistochemical stains performed on sections of the cell block demonstrated that the tumor cells were positive for vimentin, focally positive for smooth muscle actin, and positive for MIB-1 (Ki-67) in 20% of the tumor nuclei." (PMID 20436789, 2010). "Other prognostic factors include male sex; tumor necrosis; vascular invasion; rhabdoid cells; high mitotic rate; MIB1 index and DNA aneuploidy." (PMID 29147174, 2010).
tumor (continued). "MIB-1 LI also progressively increased from WNETs to WNECs and PNECs (P<0.001) and following tumour stage (P<0.05)." (PMID 19156147, 2009). "Patients were considered to present positive tumours for the expression of Ki-67/MIB-1 according to the cut-off points defined by the authors." (PMID 17453008, 2007). "The tumors were classified as low and high grade on the basis of their cellular differentiation, mitotic count, tumor necrosis and expression of MIB-1 proliferation marker." (PMID 16923196, 2006). "In particular, the tumour-proliferative rate measured as Ki-67, Mib-1 or thymidine labelling index is rapidly and significantly inhibited by hormonal treatment or chemotherapy." (PMID 16052214, 2005). "The MVD was higher in large tumours, in tumours with necrosis, a fibrotic focus, a high mitotic count or MIB1 index and presence of liver metastasis." (PMID 15558070, 2005). "A commonly used marker of tumour proliferation is Ki-67 (MIB-1), a monoclonal antibody recognising a nuclear protein expressed in all active phases of the cell cycle (G1, S, G2 and M) but absent in quiescent cells (G0)." (PMID 14760375, 2004). "The effects of treatment with anastrozole on Mib1 expression were striking and consistent in that the proportion of staining cells was always less in the treated tumour as compared with the pre-treatment biopsy." (PMID 12177804, 2002). "Compared with pre-treatment biopsies anastrozole-treated specimens displayed decreased cellularity and/or increased fibrosis in 15 tumours; changes in gland formation, nuclear pleomorphism, or mitoses, in 12 cases; and a reduction in Mib1 score in all tumours." (PMID 12177804, 2002). "The 5-year metastasis-free survival-rate for patients with tumour size ≤5 cm + MIB-1 <10% was 0.83 (95% confidence interval (CI) 0.64–0.92) compared to 0.31 (95% CI 0.11–0.53) in cases with tumour size >5 cm + MIB-1 ≥10%." (PMID 10468301, 1999). "By multivariate analysis IHC-ER, Mib1 and initial tumour size were independent predictors, the last parameter being the most important." (PMID 8912545, 1996). "The MIB-1 index correlated significantly with the mitotic activity in the tumour tissue (r = 0.33; P = 0.0001) and with the proportion of apoptotic tumour cells (r = 0.25; P = 0.0017)." (PMID 8855967, 1996). "A high percentage of Mib1-positive tumour cells (> 40%), as well as initial tumour size less than 4 cm, were also correlated with tumour responsiveness to chemotherapy (P = 0.009 and P = 0.03)." (PMID 8912545, 1996). "The 'growth fraction' of tumours can now be assessed on paraffin sections of tissues using the monoclonal antibody MIB1 by a microwave antigen retrieval technique." (PMID 7819031, 1995). "In multivariate analysis for survival, when histological grade, lymph node stage and tumour size were included as well as the MIB1 labelling index, each was found to be of independent significance." (PMID 7819031, 1995). "The strengths of the present study are as follows: This is the first report of the mutual association between the proliferation status of endothelial and tumor cells in PitNETs using AI-based tools for the evaluation of MIB1 LI in human PitNET tissue specimens." (PMID 41614857, 2025).
tumor (continued). "Lastly, we investigated the requirement of mib1 for tumor progression." (PMID 40551010, 2025). "In addition, since the immunostaining was positive for β-catenin, a common hallmark of SPN, as well as cyclin D1 and 11% positive for MIB-1, she was diagnosed with low-grade malignant SPN, despite the large size of the tumor." (PMID 39903574, 2025). "However, this triggers an overall rise in m6A levels in infected tumor cells via the IGF2BP3/MIB1/FTO feedback loop, ultimately leading to CSF3-mediated NETosis." (PMID 38167409, 2024). "A significant difference of MIB-1 LI in different histopathological types and a correlation to tumor volume at diagnosis could be shown." (PMID 38580878, 2024). "Finally, the expression levels of ccLy increase significantly with a higher MIB1/KI67 proliferation index of the tumor." (PMID 39548496, 2024). "Compared to preoperative tumor growth rates, a crucially decreasing correlation of MIB-1 LI values and postoperative tumor growth velocity could be shown after IR (linear regression analysis, n = 76, R = 0.014, R2 = 0.08, p = 0.013)." (PMID 38580878, 2024). "We assess the correlation of MIB-1 LI and tumor growth velocity (TGV), aiming to contribute to the understanding of clinical implications and the predictive value of MIB-1 LI as an indicator of proliferative activity and progression-free survival (PFS) in PLGG." (PMID 38580878, 2024). "In the current work, a significant correlation of MIB-1 LI and radiologically quantifiable tumor growth velocity could be shown for the first time." (PMID 38580878, 2024). "Consequently, it is not surprising that in the univariate analysis, p62 status appears as strong parameter likewise to tumor grade and Mib1 expression." (PMID 39131899, 2024). "MIB1 was reported as an E3 ubiquitin ligase that promoted the ubiquitination and degradation of Notch ligands, and played an important role in growth, metastasis, and micro-environment of tumor." (PMID 36849460, 2023). "Expression of the proliferation marker MIB1 exceeding 4.6% was associated with a twofold risk of tumor recurrence (p < 0.0001) while S100 immunopositivity had no independent influence on progression-free survival (p = 0.6140)." (PMID 35838837, 2023). "Despite profound gliosis in the tumor vicinity, there were very few MIB1+ and CCND1+ cells." (PMID 38066208, 2023). "Over the past decade of clinical research, IVIM-DWI derived parameters may simultaneously reflect tumor histology of microvessel density (MVD) or the percentage of MIB-1 expression positive rate(pMIB-1) both in humans and animals." (PMID 37182187, 2023). "Furthermore, CLD and TMZ combination therapy markedly reduced the number of MIB1-positive cells within the tumor." (PMID 35159037, 2022). "Furthermore, MIB-1 labeling index was demonstrated to be a reliable marker for the time to tumor progression in a prospective trial." (PMID 36091152, 2022). "Moreover, we detected the expression of MIB1 (Ki67), Vimentin, N-cadherin, and E-cadherin in the subcutaneous tumor tissues by IHC." (PMID 36522730, 2022). "The proliferation rate is given as the number of MIB1 positive cells per 100 tumor cells." (PMID 36188659, 2022). "Therefore, it is questionable if the difference in MIB1 expression alone among the different COX2 expression groups is of biological relevance regarding tumor growth." (PMID 33641674, 2021).